MYC (MYC proto-oncogene, bHLH transcription factor)
Diseases named in the same sentence as MYC in open-access papers (continued):
Sharing a sentence is not in itself a finding about the gene and the disease.
leukemia (continued). "CS1 and CS2 demonstrated suppression of leukemia proliferative activity and immune evasion, cancer cell viability, and leukemia stem cell renewal via MYC, CEBPA, and RARA axis." (PMID 41157107, 2025). "The suppression of UHRF1 downregulates leukemia stem cell signatures and MYC-related pathways in AML cells." (PMID 40508126, 2025). "Interruption of this BRD4-dependent transcriptional network is seen after treatment with BET inhibitors, including several critical regulators of myelopoiesis and leukemia, such as c-MYC, BCL2, and IRF8." (PMID 40523422, 2025). "In leukemia and certain solid tumors, MYC increases the expression of BIM, a proapoptotic protein, which can lead to cell death under specific conditions." (PMID 40148558, 2025). "Consistent with the mouse leukemia model, the loss of SETD1B reduced the MYC expression and broad H3K4me3 peaks at 4 days post-Dox treatment." (PMID 40341256, 2025). "IGF2BP3 targets mRNAs encoding important factors in leukemia, like MYC, CDK6, HOXA genes, and EPOR, causing their stabilization and overexpression in leukemia cells." (PMID 40389480, 2025). "The development of a SETD1B-specific inhibitor or an expanded application of HMT inhibitors, such as Chaetocin, which also target SETD1B, will be a valuable tool against MYC-dependent leukemia." (PMID 40341256, 2025). "Our findings unveil a novel METTL16-MXD4 oncogenic axis crucial for AML progression, establishing small-molecule inhibition of METTL16 as a potential therapeutic approach in leukemia and providing a new strategy to target MYC activity in cancer." (PMID 40946103, 2025). "Recent functional screens have demonstrated CHD4 as a dependency for leukemia-specific growth, disease maintenance, and MYC overexpression, additionally highlighting the role of this remodeling complex in leukemogenesis." (PMID 40523422, 2025). "MYC is a critical oncogene frequently upregulated in KMT2Ar leukemias, where it plays a key role in maintaining the proliferation and survival of leukemic cells." (PMID 39682203, 2024). "One of the key regulators of B cells is MYC, which promotes the migration and invasive ability of cell line leukemia cell lines." (PMID 39465162, 2024). "To test this, we performed an anti-MYC tag antibody ChIP (chromatin immunoprecipitation) to analyze the chromatin occupancy of exogenous RBM5-MYC expressed in OCIAML2 leukemia cells." (PMID 38216972, 2024). "In KMT2Ar leukemias, BRD4 is often associated with super-enhancers that drive the expression of oncogenes such as MYC, BCL2, and CDK6, which are vital for leukemic cell survival and proliferation." (PMID 39682203, 2024). "METTL14 causes the occurrence and development of leukemia by modifying MYB/MYC-targeted genes with m6A RNA, and m6A promotes the translation of c-MYC, BCL2, and PTEN in leukemia patients." (PMID 38970366, 2024). "The inhibition of BRD4 with BET inhibitors disrupts the transcriptional machinery at the level of super-enhancers, which are crucial for maintaining the high expression of MYC and other oncogenes in KMT2Ar leukemias." (PMID 39682203, 2024). "Murine and human T-ALL cells expressing CD34 and high levels of MYC have been shown to possess leukemia-initiating cell (LIC) potential." (PMID 38352301, 2024). "The TCF1-dependent NOTCH1-regulated MYC enhancer plays a fundamental role in shaping the leukemia-prone epigenetic landscape during the transition from preleukemic cells to full-blown disease." (PMID 39284807, 2024). "The BAF complex, driven by BRG1 (SMARCA4) or BRM (SMARCA2), enables transcription factors such as PU.1 and MYC to bind enhancers and promoters, sustaining oncogenic transcriptional programs essential for leukemia cell survival." (PMID 39682203, 2024). "In this study, we explored the relative expression levels of key transcription factors in leukemia cells by RT-qPCR, and the results showed that MYC, RXRB, were significantly up-regulated, while STAT1 expression was down-regulated in HAP1 compared to HS-5." (PMID 39465162, 2024).
leukemia (continued). "In contrast, Transwell experiments revealed the tangible promotion of MYC on the invasion ability of leukemia cell lines." (PMID 39465162, 2024). "Scratch healing experiments demonstrated that silencing of MYC resulted in downregulation of the migratory capacity of leukemia cell lines, implying a facilitating effect of MYC on the migratory capacity of leukemia cell lines." (PMID 39465162, 2024). "The proliferation of MYC-expressing HL-60 leukemia and MYB-expressing CRC cells (LoVo, doxorubicin-resistant LoVo/Dx, and COLO-205) was inhibited by ODNs." (PMID 38835346, 2024). "Taken together, our data suggest that PA2G4 bridges EVI1 to MYC and supports the disruption of this protein to diminish their respective oncogenic signals in this leukemia subtype." (PMID 38834613, 2024). "The NOTCH pathway and its associated proteins regulated by gene enhancers, including MYC and TCF1, are significant pathogenic factors in leukemia." (PMID 39284807, 2024). "Other approaches include disrupting MYC–MAX interaction and novel compounds such as Tosyl Chloride-Berbamine (TCB), which eliminates MYC-positive leukemia by targeting CaMKIIγ." (PMID 39682203, 2024). "Previous studies reported that YBX1 affected mRNA translation of HIF1α and MYC to promote sarcoma metastasis and leukemia progression at a posttranscriptional level." (PMID 37161388, 2023). "This specific region, 8q24.21, codes for MYC proto-oncogene, and the region, 17q22, codes for miR-142, translocation of the c-Myc locus, have been reported in leukemia patients affected by aggressive B-cell malignancy." (PMID 37887311, 2023). "For example, histidine supplementation made leukemia xenografted tumors more sensitive to methotrexate, whereas histidine depletion in a Drosophila model selectively limited the growth of MYC-dependent neural tumors." (PMID 36925958, 2023). "Degradation of EZH2 by the PROTAC-degrader MS-177 effectively inhibited on-target EZH2-PRC2 and MYC-related oncogenic nodes and inhibited leukemia growth in vivo more effectively than enzymatic inhibition." (PMID 37664059, 2023). "In both double transgenic fish, genes associated with MTORC, MYC and RAS signaling, were positively enriched in most cell clusters, consistent with their leukemia phenotypes." (PMID 36739363, 2023). "A previous report demonstrated that acute myeloid leukemia (AML) cell lines require BRD9 to sustain MYC transcription for leukemia maintenance and proliferation." (PMID 38102116, 2023). "NOTCH1 has been proven to act as a promoter for a MYC enhancer that promotes T cell development in leukemia." (PMID 37072406, 2023). "We established that the eIF4A inhibitor CR-1-31B shows therapeutic activity in MYC-driven leukemia and KRAS-driven pancreatic cancer." (PMID 36900235, 2023). "STM2457, the first METTL3 inhibitor, was validated to reduce the m6A deposit on several oncogenes (such as HOXA10 and MYC), induce cell differentiation, and effectively inhibit the growth of leukemia cells." (PMID 37028765, 2023). "c-MYC has also been found to be a potential therapeutic target in leukemia, along with other cancer types." (PMID 37624039, 2023). "The c-MYC oncogene regulates multiple cellular activities and is a potent driver of many highly aggressive human cancers, such as leukemia and triple-negative breast cancer." (PMID 37570631, 2023). "For example, in a previous study, SMARCA4 had been reported to promote the expression of the MYC oncogene specifically in leukemia, even though both MYC and SMARCA4 are expressed ubiquitously across many cell types." (PMID 36810086, 2023). "Matrine inhibits the expression of the MYC signaling pathway and has a growth inhibitory effect on human leukemia cells." (PMID 36193082, 2022).
leukemia (continued). "Suppressing UHRF1 triggered a unique gene signature in AML cells, including downregulation of the leukemia stem cell and MYC pathways." (PMID 36302855, 2022). "Mutating the GATA3 binding sites in this enhancer impacted nucleosome eviction and chromatin accessibility, resulting in decreased c-MYC expression and abrogated leukemia development in mice." (PMID 35514954, 2022). "Previously several independent reports confirmed the high levels of MYB and MYC in leukaemia and lymphomas." (PMID 34207299, 2021). "It is known that the transcriptional regulation of MYC is vulnerable to CTCF in the MLL-rearranged leukemia cell line SEM due to addiction of enhancer/promoter looping regulation at three-dimensional chromatin architecture." (PMID 34429148, 2021). "R-2-Hydroxyglutarate (R-2-HG) can also inhibit FTO activity, thereby increasing the m6A RNA modification in R-2HG-sensitive leukemia cells, reducing the stability of MYC/CEBPA transcripts, and leading to the inhibition of related pathways." (PMID 34858499, 2021). "On the other hand, HDAC7 that is mostly decreased in various types of leukemia can downregulate MYC." (PMID 34372899, 2021). "This offers an alternative approach to reactivating anti-cancer targets of BRD4 than seen in other cancer types, such as in AML or leukemia, where β-catenin mediated transcription of MYC compensates for BRD4 to drive BETi resistance." (PMID 33712563, 2021). "pDC-specific super-enhancer of RUNX2 induces high expression of MYC in leukemia cells, and promotes the survival and proliferation of BPDCN cells." (PMID 33712565, 2021). "CPI-0610, a BRD4-targeted small molecule can also reduce MYC expression in different types of leukemias." (PMID 34372899, 2021). "The combined expression of BCL2 with MYC induced leukemia in vivo with a penetrance similar to that with the MYC/HOXA9 combination, in accord with previous reports." (PMID 34310280, 2021). "Dysregulated expression of E2F and MYC families and miR-17-92 cluster are often found in the most types of cancers including lung, breast and prostate tumors or leukemia." (PMID 33430425, 2021). "The microRNA—miR-150, miR-34a, and miR-29b—have also shown significant anti-leukaemia effects by targeting wnt-signalling, mTOR signalling pathways, MYC, and Sp1/FUT4-fucosylations." (PMID 34207299, 2021). "Other key factors important for leukemia survival include MYC and BCL2, particularly in relation to venetoclax treatment." (PMID 34088716, 2021). "METTL14 inhibited hematopoietic stem cell/progenitor cell differentiation and promotes leukemia by enhancing the m6A modification of MYB (HGNC:7545)/MYC (HGNC:7553)." (PMID 35087827, 2021). "SP1 in turn regulates the expression of c-MYC and ultimately promotes the occurrence and development of leukemia." (PMID 34485297, 2021). "Specifically, these leukaemias require high levels of BRG1 for de-condensation of the cell-specific MYC enhancer." (PMID 33596994, 2021). "The demethylation activity of FTO is suppressed by R-2HG and plays critical oncogenic roles in leukemia through an FTO/m6A/MYC-CEBPA axis." (PMID 34272618, 2021). "c-MYC is a well-known oncogene in leukemia, whereas BCL2 and PTEN are negative regulators of PI3K/AKT pathway." (PMID 33611339, 2021). "Other approaches include the direct inhibition of MLL1 activity, associated metabolic pathways and protein degradation or, alternatively, the inhibitory targeting of the BRD4 domain recruited to the MYC gene, switching-off MYC-dependent leukemia." (PMID 34440566, 2021). "In contrast, all MYC/BCL2-induced leukemias were of lymphoid lineage, the half of which was B-cell type, and the other half was T-cell type, consistent with a previous report." (PMID 34310280, 2021).
leukemia (continued). "Contrary to other HDACs, HDAC7 which down-regulates MYC is mostly decreased in various types of leukemia including ones with MLL rearrangement." (PMID 34372899, 2021). "c-MYC is overexpressed during MM progression, with the highest levels detected in plasma cell leukemias." (PMID 34769070, 2021). "The combined expression of MYC/HOXA9 or MYC/MEIS1 induced leukemia in 38% and 18% of recipient mice, respectively, indicating a synergy of MYC with HOXA9 and MEIS1." (PMID 34310280, 2021). "In APL, MYC cooperates with PML-RARα to accelerate the development of leukemia, while in AML, MYC protein expression is a poor prognostic factor, particularly in patients with high risk of relapse." (PMID 32110991, 2020). "Another approach is the inhibitory targeting of proteins such as BRD4 (bromodomain-containing protein 4) recruited to the regulatory elements of the MYC gene, which can switch off the MYC-dependent leukemia sustainment program." (PMID 33302406, 2020). "Taken together, these data strongly suggest that the CDK7 inhibitor can block RNAPII loading at the BETi resistance-specific PVT1 enhancer to suppress MYC transcription, thereby exerting a synergistic anticancer effect toward BETi-resistant leukemia." (PMID 32029739, 2020). "This BRD4-independt de novo enhancer restored the enhancer-promoter looping at the MYC locus to drive MYC transcription in BETi-resistant leukemia cells." (PMID 32029739, 2020). "Regarding the biological mechanism, R-2HG was shown to inhibit FTO activity, thus increasing the m6A mRNA modification in R-2HG-sensitive leukemia cells, reducing the stability of MYC/CEBPA transcripts, and inhibiting the related pathways." (PMID 32398132, 2020). "In leukemia, well-known oncogenes (such as MYC and NRF1) were among the top edge gainers, while the well-known tumor suppressor IKZF1 is the most significant edge loser." (PMID 32728046, 2020). "Nonetheless, studies in leukemia cells and preclinical models hint that therapies targeting MYC/PP2A inhibitory network are a clinically feasible strategy for leukemia treatment." (PMID 32110991, 2020). "This differential access to regulatory regions has also been reported in murine models of MLL-AF9-driven leukemia, indicating that MYC hyperactivation during leukemia can be driven by BENC-unbalanced modulation." (PMID 32102485, 2020). "Taken together, these data indicated that BETi and THZ1 synergistically inhibited the growth of BETi-resistant leukemia cells by suppressing the expression of super-enhancer regulated oncogenic genes, as notably exemplified by MYC." (PMID 32029739, 2020). "BENC has been reported as an important super enhancer clusters for MYC expression during leukemia development." (PMID 32029739, 2020). "The c-MYC gene is very frequently activated by chromosomal translocations in hematopoietic cancers most prominently in B- or T-cell lymphoma or leukemia and much is already known about its role as a DNA binding transcriptional regulator." (PMID 33134177, 2020). "Having identified the myristoylated N‐terminal BASP1 peptide as a reagent to selectively interfere with the viability of v‐myc‐transformed cells, we explored if Myr‐NT would also inhibit the growth of leukemia cells containing high levels of endogenous MYC." (PMID 31944520, 2020). "An indirect pathway of MYC activation in ETV6/RUNX1-rearranged leukemia is mediated by the GTP-binding protein RAC1, a pivotal modulator of hematopoiesis, that increases the phosphorylation levels of STAT3." (PMID 32102485, 2020). "The treatment with JQ1 or other BET inhibitors triggers MYC downregulation with consequent cell cycle arrest and apoptosis in mouse and human leukemia cells." (PMID 32110991, 2020). "JQ1 was first reported to inhibit the proliferation of leukemia cells both in vivo and in vitro through downregulating c-MYC signaling." (PMID 32157097, 2020).
leukemia (continued). "MYC overexpression partially restored the cell growth and overcame the cell cycle arrest at G1 in both types of leukemia cells treated with BETi + THZ1." (PMID 32029739, 2020). "In leukemia, MYC activation compromised tyrosine kinase inhibitor sensitivity and functional inhibition of MYC overcame resistance by promoting differentiation." (PMID 32409685, 2020). "In the meantime, studies on leukemia indicated that m6A modification promotes the translation of oncogenes c-MYC, Bcl-2, and PTEN." (PMID 33061938, 2020). "Consistently, treatment with another FTO inhibitor R-2HG significantly elevated global m6A modification in leukemia cells, which in turn induced the degradation of MYC/CEBPA RNA transcripts and inhibited the relevant pathways." (PMID 32101138, 2020). "Instead, MYC expression is at least partially under the control of the newly formed enhancer within the PVT1 locus in BETi-resistant leukemia." (PMID 32029739, 2020). "THZ1 suppresses MYC expression by perturbing the RNAPII activity at the newly formed PVT1 enhancer in BETi-resistant leukemia cells." (PMID 32029739, 2020). "Altogether, proscillaridin A efficiently targets LSC-enriched populations, in both T-ALL and AML models marked by high MYC expression, further supporting its repurposing against MYC-dependent leukemia." (PMID 31196146, 2019). "MCL1 and MYC were also shown to cooperate in mouse models of leukemia and non-small cell lung cancer (NSCLC), and co-expression of these two factors correlates with poor NSCLC patient survival." (PMID 30674894, 2019). "R-2HG exhibits broad antiproliferative effects in high-FTO leukemia via targeting FTO/MYC/CEBPA signaling." (PMID 31921664, 2019). "This MYC SE has been previously identified in AML where Brg1 is crucial to maintain MYC expression and promote the development of leukemia." (PMID 31311566, 2019). "Proscillaridin A anticancer activity was investigated against a panel of human leukemia and solid tumor cell lines with different MYC expression levels, overexpression in vitro systems and leukemia stem cells." (PMID 31196146, 2019). "Since MYC is often overexpressed in leukemia, we compared MYC protein expression (in untreated cancer cells) with proscillaridin A IC50 values." (PMID 31196146, 2019). "Overall, these results strongly support the repurposing of proscillaridin A in MYC overexpressing leukemia." (PMID 31196146, 2019). "Here, we demonstrate that the anticancer activity of proscillaridin A correlates positively with MYC oncogenic expression in leukemia, suggesting its repurposing potential against cancer types defined by a specific molecular signature." (PMID 31196146, 2019). "Proscillaridin A produced antiproliferative effects with a preferential selectivity towards MYC overexpressing leukemia cells." (PMID 31196146, 2019). "To further confirm the role of MYC protein levels to proscillaridin A sensitivity, we transduced high MYC expressing (MOTL-4) and low MYC expressing (REH) leukemia cells, with MYC oncogene." (PMID 31196146, 2019). "Immunoblotting was used to test if HDACi modulate the leukemia-associated transcription factors β-catenin, Wilms tumor (WT1), and myelocytomatosis oncogene (MYC)." (PMID 31561534, 2019). "BRD9 is important for sustaining MYC expression via its BRD in diverse MLL-r leukemia cell lines, including MV4-11, MOLM-13, ML-2, EoL-1, and NOMO-1." (PMID 31157223, 2019). "If we limit the query to K562, a leukemia cell line, we find two enhancers downstream of the MYC gene." (PMID 30247654, 2019). "Overall, we conclude that proscillaridin A has a promising potential to be repurposed as an epigenetic drug in personalized oncology, particularly in MYC overexpressing leukemia." (PMID 31196146, 2019). "The suppression of c-MYC gene prevents leukemia initiation in mice, and reducing expression levels of c-MYC gene inhibits cell growth in refractory and relapsed T-cell acute lymphoblastic leukemia (T-ALL)." (PMID 31519186, 2019).